FGF23 (fibroblast growth factor 23)
Diseases named in the same sentence as FGF23 in open-access papers (continued):
Sharing a sentence is not in itself a finding about the gene and the disease.
cardiac hypertrophy (continued). "Subsequently, we tested whether FGF-23 could downregulate cardiac miR-30 and whether miR-30 could inhibit FGF-23–induced cardiac hypertrophy in vivo." (PMID 33848263, 2021). "In another study, myocardial injection of an adeno-associated virus carrying the FGF23 sequence led to cardiac overexpression of FGF23, but did not induce cardiac hypertrophy." (PMID 33416083, 2021). "The assumption that klotho acts as a cardioprotective reagent is also supported by our in vitro data showing prevention of cardiac Fgf23-induced cardiac hypertrophy by sKL in NRVMs without altering high intra-cardiac Fgf23 expression and secretion." (PMID 34778257, 2021). "Paradoxically, different mouse models of X-linked hypophosphatemia (XLH) as well as patients with XLH develop no cardiac hypertrophy although presenting high FGF23 level." (PMID 34422725, 2021). "As for cardiac remodeling, our data suggest that the elevation in blood pressure, but not FGF-23, plays a predominant role in cardiac hypertrophy in Dahl/SS rats, at least at an early stage." (PMID 33060834, 2020). "In this regard, the fibroblast growth factor-23 (FGF23) may be involved in the pathogenesis of atherosclerosis and myocardial hypertrophy." (PMID 32466297, 2020). "It was explored whether the effects of FGF23 on NCC expression in kidney may potentially drive physiological changes including hypertension and heart hypertrophy in a αKlotho-dependent manner." (PMID 32982979, 2020). "As discussed for cardiac hypertrophy, it is possible that FGF23-induced expression of inflammatory cytokines is not pathological, at least not initially, but has protective functions." (PMID 29770125, 2018). "FGF23 directly targets cardiac myocytes via the described FGFR4/PLCγ/calcineurin/NFAT signaling pathway and induces cardiac hypertrophy, and potentially other changes in cardiac remodeling, including cardiac fibrosis and altered cardiac metabolism, eventually resulting in reduced heart function." (PMID 29770125, 2018). "Whether up-regulation of FGF2 in the heart due to pressure overload-induced cardiac hypertrophy after TAC is also responsible for the induction of cardiac FGF23, and if so, the role of cardiac FGF23 in this setting has to be further elucidated." (PMID 29892269, 2018). "Second, patients with X-linked hypophosphatemia (XLH), genetic forms of hypophosphatemic rickets, have high serum levels of FGF23 but do not develop cardiac hypertrophy." (PMID 29770125, 2018). "To our surprise, we did not observe a rescue of heart hypertrophy, 2 weeks after spironolactone treatment, despite reduced serum Fgf23 levels." (PMID 28900153, 2017). "Although we found a profound upregulation of circulating iFgf23 as well as of cardiac and bony Fgf23 transcription after TAC, our data do not support an essential role of Fgf23 or Klotho in the pathophysiology of pressure overload-induced cardiac hypertrophy." (PMID 28900153, 2017). "Neither did the absence of Fgf23 in Fgf23−/−/VDRΔ/Δ animals protect against cardiac hypertrophy, nor did deletion of Klotho lead to further exacerbation of the TAC-induced hypertrophic phenotype, relative to VDRΔ/Δ controls." (PMID 28900153, 2017). "Despite the profound, aldosterone-mediated increase in circulating intact Fgf23 after TAC, our data do not support an essential role of Fgf23 or Klotho in the pathophysiology of pressure overload-induced cardiac hypertrophy." (PMID 28900153, 2017). "While FGF16 and FGF21 may prevent cardiac hypertrophy and fibrosis, FGF2 and FGF23 display the opposite effect." (PMID 27184924, 2016). "In contrast, FGF23 induces cardiac hypertrophy by activating calcineurin/NFAT signaling without αKlotho." (PMID 24046748, 2013). "In contrast, FGF23 elevation in the presence of low phosphate levels, as is the case in X-linked hypophosphatemia (XLH), does not seem to be associated with the development of cardiac hypertrophy in animal models or in patients." (PMID 39452290, 2024).
cardiac hypertrophy (continued). "In addition, some data show that the paracrine function of FGF23 in cardiac tissue should not be neglected, demonstrating that FGF23 promotes cardiac hypertrophy from numerous angles [R]." (PMID 36831276, 2023). "Interestingly, experimental data show that FGF-23 may, via specific myocardial FGF receptor activation, act as a mediator for cardiac hypertrophy, cardiac fibrosis, and dysfunction." (PMID 35159318, 2022). "Furthermore, a decrease of soluble Klotho in CKD was reported to be an important cause of uremic cardiomyopathy or to inhibit renal fibrosis in an FGF23-independent manner, while FGF23 can induce myocardial hypertrophy independent of Klotho." (PMID 33460402, 2021). "Mice models of XLH have excess FGF23 production, yet those mice do not develop cardiac hypertrophy." (PMID 32130720, 2020). "In line with previous experimental studies, FGF23 stimulation resulted in hypertrophic growth of NRVM and induction of atrial natriuretic peptide (ANP) and brain natriuretic peptide (BNP), well-established markers for cardiac hypertrophy, which were inhibited by co-treatment with CsA." (PMID 31540546, 2019). "However, neither spironolactone treatment nor FGF23 knockout alters the induction of FGF2 in the high blood pressure-induced cardiac hypertrophy through TAC." (PMID 29892269, 2018). "First, although serum FGF23 levels are elevated following pressure overload via transaortic constriction in mice, FGF23 does not appear to be required for the development of pathologic cardiac hypertrophy in this animal model." (PMID 29770125, 2018). "Moreover, we demonstrated that FGF23 contributes to pathologic cardiac remodeling and promotes the pro-fibrotic crosstalk between cardiac myocytes and fibroblasts resulting in enhanced cardiac hypertrophy and fibrosis in the absence of klotho." (PMID 29977226, 2018). "Overall, primary forms of pathologic cardiac remodeling might not require FGF23, and not every scenario of FGF23 elevations might result in cardiac hypertrophy." (PMID 29770125, 2018). "Moreover, FGF23 provoked cardiac hypertrophy through calcineurin/NFAT signaling without αKlotho co-receptor." (PMID 28974056, 2017). "Of note, animals on high phosphate diet for 6 months exhibited significantly lower FGF23 levels than animals that were fed the diet for 3 months, which was also accompanied by a slight reduction of cardiac hypertrophy that missed statistical significance, but not of cardiac fibrosis." (PMID 28512310, 2017). "Our findings suggest that FGF23 acutely increases intracellular calcium levels and cardiac contractility, but that sustained activation of cardiac FGFR4 might induce changes that progress to pathologic remodeling including cardiac hypertrophy and fibrosis." (PMID 28512310, 2017). "However, our data indicate that absence of a functioning VDR does not blunt the pro-hypertrophic actions of FGF23 in vivo, and does not interfere with the TAC-induced increase in circulating Fgf23 or with the TAC-induced cardiac hypertrophy." (PMID 28900153, 2017). "Whether cardiac FGF23 is increased among non-CKD patients with cardiac hypertrophy should be investigated in future studies." (PMID 27400031, 2016). "Several experimental studies have demonstrated that fibroblast growth factor 23 (FGF23) may induce myocardial hypertrophy via pathways independent of α-Klotho, its co-factor in the induction of phosphaturia." (PMID 27400031, 2016). "Elevated FGF23 levels are associated with all-cause and CV mortality in the general population as well as in CKD patients, LV dysfunction and atrial fibrillation (AF) in patients without CV co-morbidities, and the development of cardiac hypertrophy and fibrosis." (PMID 34422725, 2021).
cardiac hypertrophy (continued). "Interestingly, our findings that cardiac overload did not enhance skeletal expression of FGF23 are consistent with the study of cardiac hypertrophy, but not with another study showing that myocardial infarction induced FGF23 expression in the bone as well as the heart." (PMID 34765890, 2021). "In experimental heart hypertrophy induced by transverse aortic constriction in wild-type and Fgf23/Vdr-double knockout mice, hypertrophic remodelling, left ventricular functional impairment or left ventricular fibrosis developed independent of the presence of FGF23." (PMID 33416083, 2021). "The stimulation of this pathway by FGF23 could uniquely act on the FGFR 4 receptor in cardiomyocytes, then prevent part of the function of FGFR, inhibit myocardial hypertrophy-related genes, and slow down the process of myocardial hypertrophy and myocardial fibrosis." (PMID 34992536, 2021). "Our data confirm that FGF23-induced hypertrophic growth of cardiomyocytes is mediated by calcineurin/NFAT signaling and support the hypothesis that FGF23-mediated activation of local RAAS in the heart promotes cardiac hypertrophy and fibrosis in vitro and in vivo." (PMID 31540546, 2019). "Several previous studies have suggested that FGF23 may promote cardiac hypertrophy via FGF receptor 4 (FGFR4)-mediated activation of the calcineurin-NFAT signaling pathway, although to what extent circulating FGF23 reflects myocardial FGF23 in the setting of heart failure remains under discussion." (PMID 27400031, 2016). "In the current study, the relationship between FGF23 and cardiac hypertrophy differed according to CKD stage; therefore, whether or not differences between the various CKD stages might be explained by variations in the cardiac expression of FGFR4 awaits further investigation." (PMID 27400031, 2016). "Hence at high concentration FGF23 could stimulate cardiac hypertrophy even in the absence of αKlotho." (PMID 23825530, 2013). "Surprisingly, although FGF23 neutralization improved serum PTH and 1,25-dihydroxyvitamin D levels, there was no impact on the parameters concerning myocardial hypertrophy." (PMID 30087898, 2018). "Our study suggests that in physiologic cardiac hypertrophy, the heart produces FGF23 that contributes to hypertrophic growth of cardiac myocytes in a paracrine and FGFR4-dependent manner, and that the kidney does not respond to heart-derived FGF23." (PMID 39452290, 2024). "Given that FGF receptor 4 is responsible for the pathologic functions of FGF23, selective FGF receptor 4 blockers might be more specific to target FGF23-induced cardiac hypertrophy and do not interfere with the physiologic functions of FGF23." (PMID 30200452, 2018). "In our study we provided evidence that Fgf23 is not essentially mediating pressure-induced cardiac hypertrophy in a TAC model, using two independent approaches: i) by spironolactone-induced Fgf23 suppression in WT mice, and ii) by genetic deletion of Fgf23 in Fgf23−/−/VDRΔ/Δ mice." (PMID 28900153, 2017).
heart failure (136 papers, 2013 to 2025). Inability of the heart to pump blood at an adequate rate to meet tissue metabolic requirements. "FGF23 regulates cell proliferation and the reabsorption of phosphate by the kidney and is associated with heart failure and impaired host response to infection." (PMID 40687705, 2025). "Observational studies and clinical trials have shown an association between raised FGF-23 and mortality, heart failure, and CKD progression in multiple cohorts." (PMID 41561945, 2025). "FGF-23 is known to be an independent risk factor in numerous cardiovascular diseases, including coronary heart disease, heart failure and hypertrophic cardiomyopathy." (PMID 41226753, 2025). "Among ACS patients, a correlation between FGF23 levels and the likelihood of cardiovascular death, heart failure hospitalization, and all-cause mortality was observed." (PMID 38846254, 2024). "In this regard, we have found that elevated FGF-23 levels were independently associated with an increased risk of composite CV death or hospitalization for heart failure after ACS." (PMID 38541889, 2024). "Other studies have demonstrated a significant interaction between FGF-23 and kidney function regarding the risk of cardiovascular death, all-cause mortality or incident heart failure." (PMID 38524235, 2024). "A recent study of 172 patients with heart failure and preserved ejection fraction showed that higher FGF-23 levels were independently linked to lower peak oxygen consumption and shorter six-minute walk distance at the initial assessment." (PMID 38541889, 2024). "The association of higher FGF-23 levels with the development of heart failure has also been described in patients with acute heart failure and even in the general population." (PMID 38541889, 2024). "Due to the wide range of systems in which FGF23 participates, this protein has emerged as a potential biomarker for cardiovascular risk, with high levels associated with adverse outcomes such as heart failure and arrhythmias." (PMID 38732094, 2024). "The combination of increased FGF23 and low Klotho – a FGF23 cofactor – levels is associated with a higher risk of cardiovascular death or heart failure (HF) hospitalization in subjects with stable ischemic heart disease." (PMID 37658340, 2023). "Large epidemiological studies have shown a strong associations between FGF23 concentration and the risks of cardiovascular disease, especially heart failure and stroke, and mortality." (PMID 37593148, 2023). "The minimum detectable ORs for coronary artery disease, stroke, and heart failure per FGF-23 increasing allele were 1.13, 1.26, and 1.18, respectively." (PMID 36719157, 2023). "Previous observational studies have demonstrated that the circulating concentration of FGF23 is related to heart failure (HF), and this association appears to be stronger in patients with CKD, but is not affected by adjustment for kidney function." (PMID 36909314, 2023). "In clinical studies elevated FGF-23 was associated with left ventricular (LV) hypertrophy and was shown to be a strong predictor of cardiovascular mortality in patients with heart failure and reduced (HFrEF) or preserved (HFpEF) LV ejection fraction." (PMID 36790465, 2023). "Genetically high FGF23 concentrations have also been shown to be associated with a higher risk of heart failure in a biobank cohort." (PMID 36909314, 2023). "It finally appeared that an increased level of FGF23 was associated with subclinical cardiac disease, new heart failure (HF), and a 14% greater risk of IHD." (PMID 35736431, 2022). "In a large cohort of patients with recent acute coronary syndromes, an elevated level of FGF-23 was associated with the risk of adverse outcomes, including cardiovascular death or heart failure hospitalization." (PMID 35211520, 2022). "Specifically, it has been shown that levels of serum phosphate and FGF-23 associate with cardiovascular events and mortality in patients with heart failure." (PMID 34222283, 2021).
heart failure (continued). "One of the reasons for this phenomenon is that increased blood FGF‐23 concentrations increase the risk of cardiovascular comorbidities, such as myocardial infarction and heart failure in humans." (PMID 34418162, 2021). "A clinical investigation suggested that FGF-23 can be a novel risk factor for coronary artery disease and heart failure in the general population." (PMID 35008591, 2021). "Univariate associations remained after adjusting for heart failure and estimated glomerular filtration rate, known confounders of NT-proBNP and FGF23." (PMID 33534825, 2021). "Recently, the association of FGF-23 with mortality is extended to individuals with heart failure with preserved ejection fraction, and to populations with known prevalent CVD." (PMID 34297744, 2021). "Lower FGF23 levels in the treatment arm are associated with lower risk of cardiovascular mortality and cardiovascular events such as heart failure and sudden cardiac deaths." (PMID 33416083, 2021). "Elevated fibroblast growth factor 23 (FGF23) is associated with cardiovascular events, particularly heart failure." (PMID 34765890, 2021). "A high circulating FGF-23 level was reported to be associated with high risks of cardiovascular diseases, heart failure, and mortality in the elderly population." (PMID 35008591, 2021). "An independent association was reported between elevated levels of FGF23 in the serum of heart failure patients with reduced EF or preserved EF." (PMID 34095143, 2021). "At least part of the excess mortality seems to be attributable to cardiovascular disease and, more specifically, FGF23 has been linked with a higher risk of (progressive) heart failure." (PMID 32857288, 2020). "Most epidemiological studies in the general population, one consisting of eleven thousand participants, also found an association between FGF23 and heart failure." (PMID 32130720, 2020). "A recent meta-analysis of prospective cohort studies reported that higher FGF23 levels were associated with an elevated risk of all-cause mortality, cardiovascular disease events, cardiovascular mortality, stroke, and heart failure." (PMID 28977159, 2017). "Elevated serum phosphate concentrations have been associated with cardiovascular events including heart failure through its interactions with parathyroid hormone, vitamin D, and fibroblast growth factor 23 in some studies." (PMID 27716206, 2016). "Meanwhile, although both low serum total 25(OH)D and high intact FGF23 concentrations were associated with cardiovascular events including heart failure in the univariate analysis, only intact FGF23 remained significant in a multivariate analysis." (PMID 25883412, 2015). "In human studies, higher circulating concentrations of FGF-23 have been associated with increased left ventricular mass as well as incident heart failure, myocardial infarction, and cardiovascular death." (PMID 25647414, 2015). "High FGF23 levels have been associated with other complications in this setting such as atrial fibrillation, heart failure, and vascular calcification." (PMID 26491212, 2015). "In particular, significant associations between higher FGF23 concentrations and increased risk of heart failure, total and hemorrhagic stroke myocardial infarction, CHD, all cause and cardiovascular mortality emerged." (PMID 26193703, 2015). "FGF23 was also positively associated with risk of incident heart failure (HF) and total cardiovascular events in the Cardiovascular Health Study and with cardiovascular mortality in the Uppsala Longitudinal Study of Adult Men." (PMID 26459301, 2015). "Heart failure was associated with FGF23, IGFB-7, GDF-15, IL-6, and MyBPC3." (PMID 40496590, 2025). "The association between FGF-23 and hsCRP with composite CV death or hospitalization for heart failure (HHF), HHF, CV death, and major adverse CV events were assessed using multivariable Cox proportional hazard models adjusted for clinical risk factors, and markers of cardiac and renal injury." (PMID 41151250, 2025).